OR5AL1 (olfactory receptor family 5 subfamily AL member 1 (gene/pseudogene))
Description:
Odorant receptor.
Synonyms: OR5AL1P
Gene: Protein-coding gene on chromosome 11 (56,412,696 to 56,413,680, forward strand). Ensembl gene ENSG00000272987.
Subcellular location: Cell membrane
Pathways (Reactome):
Sensory Perception: Expression and translocation of olfactory receptors
Homologues: Orthologues: mouse Or5al1 (41% identical), rat Or5al1 (41% identical), mouse Or5al5 (41% identical), mouse Or5al6 (40% identical), rat Or5al5b (39% identical). Paralogues in human: OR8U3 (33% identical), OR8U1 (32% identical), OR8K3 (31% identical), OR8J2 (30% identical), OR8K5 (30% identical), OR8J1 (29% identical), OR8K1 (29% identical), OR8J3 (29% identical), OR5AP2 (24% identical), OR5J2 (23% identical), OR5M8 (23% identical), OR8D1 (23% identical), and 84 more.